PTH (parathyroid hormone)
Diseases named in the same sentence as PTH in open-access papers (continued):
Sharing a sentence is not in itself a finding about the gene and the disease.
atherosclerosis (continued). "Elevated parathyroid hormone levels and inflammation during intense exercise may further promote atherosclerosis." (PMID 40373527, 2025). "This suggests that PTH might affect the development of atherosclerosis by altering vascular compliance." (PMID 29088221, 2017). "One possible explanation is that atherosclerosis might mediate a link between serum vitamin D, PTH and cardiovascular disease (CVD)." (PMID 29088221, 2017). "It is the first study of its kind that includes measures of PTH and corrected calcium in conjunction with vitamin D. We could also analyze data with respect to novel markers of atherosclerosis and vascular disease, such as PWV and carotid IMT." (PMID 26078787, 2015). "Elevated PTH may increase mortality through its effects on cardiac muscle contractility and its ability to promote atherosclerosis and vascular calcification." (PMID 24073266, 2013). "Previous studies have supported that vitamin D may reduce the risk of CVD by blocking the renin-angiotensin system, decreasing the parathyroid hormone levels, reducing inflammation, lowering coagulation, subsequently reducing atherosclerosis, and increasing insulin production." (PMID 39194949, 2024). "Moreover, it was not related to conventional indices of atherosclerosis, but to other non-traditional risk factors, as serum Parathyroid hormone levels." (PMID 26131456, 2015). "Finally, the Multi-Ethnic Study of Atherosclerosis, a large prospective cohort study, the authors observed a complete lack of association of 25OHD and PTH with baseline cIMT and plaque prevalence and progression of these markers of subclinical atherosclerosis at follow-up." (PMID 28840128, 2017). "The potential of mineral metabolic disturbances, including FGF23, α-klotho, PTH, phosphate, and vitamin D status, as non-traditional biomarkers of atherosclerosis is still under debate." (PMID 36221075, 2022). "Additionally, one could postulate that higher intact-PTH level, which was related to impaired endothelial function and increased aortic pulse pressure, may also help explain previously observed correlations of elevated intact-PTH with both atherosclerosis disease and failing AVF33." (PMID 27101807, 2016). "Indeed, the relationship, if any, of the main mineral metabolism factors (i.e., calcium, phosphate, 25-hydroxyvitamin D (vitamin D), FGF23, a-klotho, PTH) with subclinical atherosclerosis burden in T1D subjects, in the absence of kidney impairment has not been assessed yet." (PMID 36221075, 2022). "did not prove a link between serum concentrations of atherosclerosis markers (brain natriuretic peptide, CRP and tumor necrosis factor-ɑ) and PTH or calcium levels." (PMID 37842310, 2023).
familial hypocalciuric hypercalcemia (44 papers, 2012 to 2026). Familial hypocalciuric hypercalcemia (FHH) is a generally asymptomatic genetic disorder of phosphocalcic metabolism characterized by lifelong moderate hypercalcemia along with normo- or hypocalciuria and elevated plasma parathyroid hormone (PTH) concentration. "Loss-of-function mutations of CaSR at 1 or both alleles inhibit CaSR signaling and cause increased PTH secretion, referred to as familial hypocalciuric hypercalcemia 1 (FHH1) and neonatal severe hyperparathyroidism (NSHPT), respectively." (PMID 36099030, 2022). "Taken together, the novel D99N homozygous mutation in the CaSR gene reduces CaSR activity, leading to reduced sensitivity of parathyroid cells to extracellular Ca2+ and abnormal PTH secretion, thereby causing more severe hypocalciuric hypercalcemia." (PMID 35095753, 2021). "Indeed, some of our subjects with raised PTH concentrations in autumn might have a variant of Familial Hypocalciuric Hypercalcemia (i.e. raised PTH with total calcium at the upper reference range)." (PMID 36187131, 2022). "The condition, also known as “familial benign hypercalcemia”, is genetically heterogeneous and results from mutations that cause parathyroid gland insensitivity to extracellular calcium with a resulting rightward shift of the set point for suppression by calcium of PTH secretion." (PMID 33716975, 2021). "Familial hypocalciuric hypercalcemia is a rare condition characterized by low urinarycalcium levels, with slightly elevated blood calcium and PTH levels." (PMID 40893023, 2025). "In this study we present a new mouse model for familial hypocalciuric hypercalcemia (FHH1) due to an inactivating Casr mutation and analyze to which extent the phenotype is dependent on PTH." (PMID 38386045, 2024). "Inactivating mutations most often cause familial hypocalciuric hypercalcemia (FHH), a lifelong condition characterized by elevated serum calcium values, high-to-normal PTH concentrations and low renal calcium excretion." (PMID 35506149, 2022). "Familial hypocalciuric hypercalcemia (FHH, [OMIM #145980]) is recognized as a benign endocrine condition affecting PTH and calcium levels due to heterozygous inactivating mutations in the calcium sensing receptor (CaSR)." (PMID 34659108, 2021). "The diagnosis was suggested to be hypocalciuric hypercalcemia but was different from familial or acquired hypocalciuric hypercalcemia which were featured by elevated PTH level." (PMID 28487781, 2017). "It has been suggested that elevated FGF23 levels may distinguish FHH1 from other forms of PTH-dependent hypocalciuric hypercalcemia." (PMID 38386045, 2024). "Familial hypocalciuric hypercalcemia (FHH) is a mostly benign condition of elevated calcium and PTH levels based on a hyposensitive calcium sensing receptor (CaSR) in FHH 1 or its downstream regulatory pathway in FHH2 and FHH3." (PMID 35566721, 2022). "Familial hypocalciuric hypercalcemia (FHH) is an autosomal dominant disorder characterized by modestly elevated serum calcium (Ca), inappropriately high parathyroid hormone (PTH) levels and low urinary Ca excretion." (PMID 22620673, 2012). "The mean PTH and calcium concentrations at the time of 18F-FCH PET/CT were 118 pg/mL (range: 15–746) and 2.54 mmol/L (range: 2.22–3.05), respectively; 4/42 (10%) patients had multiple endocrine neoplasia type-1 (MEN-1), and 1/42 (2%) had familial hypocalciuric hypercalcemia (FHH)." (PMID 34943620, 2021).
breast carcinoma (41 papers, 1995 to 2025). "Although not statistically significant, small proportions of the association between PCB153 and breast cancer were mediated by estradiol and PTH, with the overall mediated effect being 6.4 and 4.1%, respectively." (PMID 39548533, 2024). "In advanced cancers, such as those caused by 4T1 breast cancer cells, PTH suppresses the expression of Pthlh in tumors, slowing the tumor–bone vicious cycle and leading to reduced incidence of bone metastases." (PMID 36692956, 2023). "The aim of this investigation was to evaluate potential association between PTH gene polymorphism and breast cancer risk among Kazakhstani women." (PMID 29805904, 2014). "Further studies are required to confirm our results and clarify role of PTH gene genotypes on breast cancer risk." (PMID 29805904, 2014). "The aim of this study was to examine pre-diagnostic levels of vitamin D (25OHD), PTH and calcium in relation to survival after breast cancer." (PMID 24952509, 2014). "When studying pre-diagnostic levels of PTH, there was also a higher breast cancer-specific mortality among subjects in the first 1.31 (0.81–2.12) as well as in the third 1.20 (0.73–1.96) tertile; however, the results were not statistically significant." (PMID 24952509, 2014). "Previous experimental studies have suggested that PTH may be associated with poor breast cancer survival due to carcinogenic and tumor promoting effects, such as regulating angiogenesis and osteoclastogenesis in bone metastasis by breast cancer cells." (PMID 24952509, 2014). "In this analysis, we could not find statistically significant associations between pre-diagnostic levels of PTH and breast cancer survival and also the association between levels of calcium and breast cancer mortality was weak." (PMID 24952509, 2014). "It has been suggested in experimental studies that PTH has a carcinogenic and tumor promoting effect, and it has also been indicated that primary hyperparathyroidism may increase the risk of breast cancer." (PMID 24952509, 2014). "Single nucleotide polymorphisms in the gene encoding the parathyroid hormone (PTH) are associated with breast cancer development risk, and may modify the associative interaction between the levels of calcium intake and breast cancer." (PMID 29805904, 2014). "Therefore, there is a risk of misclassification of PTH levels that may have attenuated a potential possibly obscure true association between pre-diagnostic levels of PTH and mortality from breast cancer." (PMID 24952509, 2014). "Breast cancer cells that metastasize to bone secrete parathyroid hormone-related peptide (PTHrP), which activates PTH/PTHrP receptors (PTHR1) on osteoblasts, leading to the release of receptor activator of nuclear factor-kappaB (RANK) ligand." (PMID 40941030, 2025). "The top 5 keywords of centrality were “Breast cancer”, “Adipose tissue”, “Bone formation”, “Age” and “Parathyroid hormone”." (PMID 39817378, 2025). "The role of parathyroid hormone (PTH)-related protein (PTHrP) in breast cancer remains controversial, with reports of PTHrP inhibiting or promoting primary tumor growth in preclinical studies." (PMID 38409028, 2024). "Although not statistically significant, there was a suggestive mediation through estradiol and PTH in the association of NO2 and PCB153 exposures with breast cancer risk." (PMID 39548533, 2024). "In a study testing the effect of PTH on breast cancer bone metastases in a mouse model, it was reported that PTH treatment reduced tumor ingrowth into bone, reduced metastasis, preserved bone microarchitecture, and prolonged survival of mice." (PMID 38474093, 2024). "In 4T1 breast cancer cells, PTH decreased expression of PTH-related protein (PTHrP), implicated in the vicious cycle of bone metastases." (PMID 36692956, 2023). "Collectively, these data suggest an interplay of events among PTH1R, PTH, and PTHrP, particularly in breast cancer–mediated skeletal metastasis, and offer new directions for research." (PMID 36692956, 2023).
breast carcinoma (continued). "Ablation of Gsα, a downstream mediator of PTH1R signaling in bone, abolishes the inhibitory effects of PTH treatment on breast cancer bone metastasis." (PMID 36692956, 2023). "In this study, we establish a critical role for PTH1R in the actions of intermittent PTH in reducing bone metastasis in mouse models of breast cancer." (PMID 36692956, 2023). "The circulating protein in question was later identified as a distinct protein with a region of high similarity to the PTH molecule and was purified from a number of cell lines, including a breast cancer cell line." (PMID 37345007, 2023). "KEGG pathway analyses showed that miR-335-5p target genes are predicted to associate with: Steroid biosynthesis, Parathyroid hormone synthesis, secretion and action, Ras signaling pathway, PI3K-Akt signaling pathway, and breast cancer." (PMID 36992332, 2023). "Overall, these results demonstrate that PTHrP is an important mediator of breast cancer cell migration toward the bone and suggest that inhibition of migration by PTH is mediated, at least in part, by suppression of PTHrP expression." (PMID 36692956, 2023). "Breast cancer cells produce molecules similar in structure to parathyroid hormone (PTH), which promote cells that build up or break down bone." (PMID 38148788, 2023). "In this study, we examined the role of PTH1R signaling in both breast cancer cells and osteoblasts in influencing breast cancer skeletal metastases in response to intermittent PTH." (PMID 36692956, 2023). "Although the main physiological function of PTH signaling involves the regulation of calcium homeostasis, PTHrP functions more as a multifunctional cytokine, and its role in breast cancer and metastasis has been well studied." (PMID 36692956, 2023). "Using shRNA and transgenic models with impaired PTH1R signaling, we demonstrate that PTH1R is required in both breast cancer cells and osteoblasts for PTH to reduce breast cancer bone metastases in mice." (PMID 36692956, 2023). "In conclusion, we demonstrate, using transgenic models and shRNA knockdown, that PTH1R signaling is critical in both breast cancer cells and osteoblasts for the inhibitory actions of PTH treatment on bone metastases." (PMID 36692956, 2023). "Parathyroid hormone synthesis, secretion, and action, glyoxylate and dicarboxylate metabolism, breast cancer, and basal cell carcinoma were the major KEGG pathways." (PMID 36704356, 2022). "In this study, patients and controls showed similarity in PTH levels, corroborating a study in breast cancer." (PMID 35919232, 2022). "By the 1980s multiple independent groups had eventually purified a protein similar in structure and biological function to PTH from human lung cancer, breast cancer, and renal cell carcinoma cell lines." (PMID 33828987, 2021). "Our case is unique because of the intrathoracic administration of the PTH regimen forthe treatment of recurrent HER2+ breast cancer with large chest walldisease, as well as the distant metastasis." (PMID 30241190, 2018). "Our case strongly suggests the need to further explore the use of intrapleuralchemotherapy as a novel treatment modality in metastatic cancer with pleural orchest wall diseases, including PTH for HER2+ breast cancer." (PMID 30241190, 2018). "We used an in vivo model to determine how increasing the number of cells of the osteoblast lineage with parathyroid hormone (PTH) modified subsequent skeletal colonization by breast cancer cells." (PMID 30261597, 2018). "BALB/c nude mice were injected for five consecutive days with PBS (control) or PTH and then injected with DiD-labelled breast cancer cells via the intra-cardiac route." (PMID 30261597, 2018). "PTH released during this misbalance of bone turnover has been shown to enhance tumor growth by increasing the osteoblasts in a mouse model of breast cancer and myeloma-bearing rats." (PMID 29642534, 2018).
breast carcinoma (continued). "To examine this, breast cancer cells were injected into animals at time points where we had determined osteoblastic cell numbers would be increased in response to treatment with PTH." (PMID 30261597, 2018). "There are no previous results reported from epidemiological studies on PTH and breast cancer survival, and our explorative analysis is the first within the area." (PMID 24952509, 2014). "MDA-MB-231 breast cancer cells have been treated with PTH 100 nM and Vitamin D 100 nM and total cell lysates have been extracted." (PMID 20831823, 2010). "We have investigated the expression of the PTH/PTHrP receptor by the human breast cancer cell lines MCF-7, ZR-75-1, T-47-D, SK-BR-3, Hs578T and MDA-MB231." (PMID 7599071, 1995). "PTH, acting through PTH1R, plays a key role in the bone–breast vicious cycle, altering several key genes implicated in bone metastases and rendering the niche less favorable to the homing of breast cancer cells." (PMID 36692956, 2023). "To determine whether suppression of PTHrP is required for inhibition of 4T1 breast cancer cell migration by PTH treatment, we knocked down Pthlh in 4T1 cells (PthlhKD-4T1 cells) using siRNA." (PMID 36692956, 2023). "This is supported by the data demonstrating that breast cancer cells are unresponsive to PTH or PTHrP treatment, and by the fact that PTH and abaloparatide lack the PTHrP midregion, NLS, and C-terminus, which appear critically important for PTHrP to directly regulate breast tumor progression." (PMID 37345007, 2023). "Preclinical studies from our laboratory have demonstrated that anabolic PTH decreases both the tumor engraftment rate and the incidence of spontaneous breast cancer metastases to bone in orthotopic models of both human and murine breast cancer tumors and prolongs survival in mice." (PMID 36692956, 2023). "In conclusion, PTH1R expression is crucial in both osteoblasts and breast cancer cells for PTH to reduce bone metastases, and in breast cancer cells, this may be mediated in part by suppression of PTHrP." (PMID 36692956, 2023). "PTHrP is a key mediator of the actions of PTH on breast cancer cell migration." (PMID 36692956, 2023). "PTH1R is expressed in many tissues that also express PTHrP, including breast cancer cells.The anabolic actions of PTH on PTH1R are mediated by the stimulatory G protein Gs, which activates adenylyl cyclase, leading to an increase in cAMP levels and the activation of the PKA pathway." (PMID 36692956, 2023). "The result of KEGG enrichment analysis showed that there were three significant enriched pathways, i.e., two were related to cancer, i.e. pathway in cancer and breast cancer, and the other was the pathway of parathyroid hormone synthesis, secretion, and action." (PMID 34667146, 2021). "However, pre-treatment of mice with intermittent PTH in an orthotopic 4T1 breast cancer model didn't affect the primary tumor volume." (PMID 32117726, 2020). "The most significant novel finding we present is that increasing the osteoblastic cell population with PTH resulted in breast cancer cells subsequently arriving in this modified environment, forming significantly higher numbers of skeletal tumours outside the hind limbs compared to control." (PMID 30261597, 2018). "This is the first demonstration that PTH-induced stimulation of osteoblastic cells may result in alternative skeletal sites becoming available for breast cancer cell colonization." (PMID 30261597, 2018). "Furthermore, the results highlight the importance for additional investigations into the use of PTH as an anabolic agent in the treatment of breast cancer bone metastases to gain a clearer understanding of the role of the osteoblast in metastatic disease." (PMID 30261597, 2018). "Total difference (between the group with breast cancer and the control group) in allele frequencies for PTH polymorphism was not significant (p > 0.05)." (PMID 29805904, 2014).